SNHG18 (small nucleolar RNA host gene 18)
Gene: Long non-coding RNA gene on chromosome 5 (9,545,647 to 9,597,347, forward strand). Ensembl gene ENSG00000250786.
Gene Ontology:
Biological process: RNA processing
Cellular component: nucleolus
Diseases named in the same sentence as SNHG18 in open-access papers:
SNHG18 is named in the same sentence as 19 diseases in open-access papers, as found by Europe PMC text mining. Sharing a sentence is not in itself a finding about the gene and the disease. The quoted sentences say what the papers report.
glioma (24 papers, 2018 to 2024). A benign or malignant brain and spinal cord tumor that arises from glial cells (astrocytes, oligodendrocytes, ependymal cells). "This study aims to probe the biological functions of long non-coding RNA small nucleolar RNA host gene 18 (SNHG18) on glioma cells and its underlying mechanism." (PMID 34937497, 2022). "In this work, consistently, it was found that SNHG18 expression was elevated in glioma tissues and associated with poor prognosis of GBM patients." (PMID 34937497, 2022). "Our work implies that SNHG18 has the potential to become a diagnostic marker and molecular therapy target for glioma." (PMID 34937497, 2022). "LncRNA small nucleolar RNA host gene 18 (SNHG18) expression is elevated in glioma, and it is linked to the enhanced radioresistance of glioma cells." (PMID 34937497, 2022). "Small nucleolar RNA host gene 18 (SNHG18) is significantly upregulated in clinical glioma tissues and is negatively associated with semaphorin 5A (Sema5A) expression." (PMID 31391206, 2019). "We also described the relevance of ENO1 in SNHG18-mediated glioma migration and investigated the underlying mechanisms." (PMID 31798634, 2019). "Moreover, survival analysis was performed with the GEPIA database, and the results authenticated that high SNHG18 was in association with a shorter overall survival time of glioma patients." (PMID 34937497, 2022). "Nonetheless, the underlying mechanisms of SNHG18 in glioma pathogenesis are largely unclear." (PMID 34937497, 2022). "Moreover, chi-square test indicated that SNHG18 high expression was associated with an increase in glioma grade." (PMID 34937497, 2022). "Previous studies have reported that SNHG18 functions as a tumor suppressor in liver cancer, but as an oncogene in non-small cell lung cancer, glioma, and multiple myeloma." (PMID 36927398, 2023). "SNHG18 is a potential metastatic feature evidenced in several types of cancer, including hepatocellular carcinoma, lung cancer, and glioma." (PMID 37644825, 2023). "Previous studies have found that SNHG18 is abnormally expressed in glioma tissue specimens, and high expression of SNHG18 in gliomas enhances their radiation resistance." (PMID 36597032, 2023). "SNHG18 inhibits Semaphorin 5A (SEMA5A) through competing endogenous RNAs (ceRNAs) to promote drug resistance in gliomas, and SNHG18 expression is related to tumor degree in gliomas." (PMID 36927398, 2023). "It is also reported that SNHG18 promotes the epithelial-mesenchymal transition, migration and invasion of glioma cells." (PMID 34937497, 2022). "In glioma, it is reported that SNHG18 inhibits the nucleocytoplasmic transport of α-enolase, thus promoting glioma cell migration." (PMID 34937497, 2022). "SNHG18 directly targeted the miR-338-5p/FOXD1 axis, and miR-338-5p inhibition weakened the inhibiting effects of SNHG18 knockdown on proliferation, migration and invasion of glioma cells." (PMID 34937497, 2022). "Mechanistically, it is revealed that E2F1 is a regulator for SNHG18/miR-338-5p/FOXD1 axis in glioma." (PMID 34937497, 2022). "In summary, this work demonstrates that knocking down SNHG18 suppresses the malignant phenotypes of glioma cells via modulating miR-338-5p and FOXD1." (PMID 34937497, 2022). "Our data suggest that SNHG18/miR-338-5p/FOXD1 axis is a vital downstream mechanism by which E2F1 participates in regulating glioma progression." (PMID 34937497, 2022). "In this work, we substantiated that miR-338-5p was a target of SNHG18; SNHG18 facilitated malignant biological behaviors of glioma cells via adsorbing miR-338-5p." (PMID 34937497, 2022). "Another study reports that SNHG18 is overexpressed in glioma, and overexpression of SNHG18 reduces the radiosensitivity of glioma cells via inhibiting semaphorin 5A." (PMID 34937497, 2022). "Representative counting of migration and invasion assays after knockdown of DGCR10, HAR1B, and SNHG18 in different glioma cell lines." (PMID 34540695, 2021).
glioma (continued). "This cluster of immature cells was also characterized by SNHG18, known to play an oncogenic role in glioma, LINC0052, which acts as a sponge for miR-608, and the annotated transcripts AC026124.1, AL132780.2, and AC026401.3." (PMID 33445654, 2021). "Real-time quantitative PCR (RT-qPCR) was carried out to detect the expression levels of DGCR10, HAR1B, and SNHG18 in five glioma cell lines." (PMID 34540695, 2021). "Another group confirmed that lncRNA SNHG18 promoted glioma cell motility by disrupting the nucleocytoplasmic shuttling of ENO1." (PMID 34627260, 2021). "Next, nucleocytoplasmic fractionation was performed to determine the locations of DGCR10, HAR1B, and SNHG18 in glioma cells." (PMID 34540695, 2021). "A nine-EMT-related lncRNAs (HAR1A, LINC00641, LINC00900, MIR210HG, MIR22HG, PVT1, SLC25A21-AS1, SNAI3-AS1, and SNHG18) signature was identified in patients with glioma." (PMID 34288803, 2021). "Knockdown of DGCR10 and HAR1B promoted, whereas knockdown of SNHG18 inhibited the migration and invasion of gliomas." (PMID 34540695, 2021). "The relative expression level of DGCR10, HAR1B and SNHG18 in different glioma cell lines after knockdown." (PMID 34540695, 2021). "Given that the functions of DGCR10, HAR1B, and SNHG18 are rarely studied in gliomas, the patients from the TCGA database were classified into high- and low-expression groups according to the median expression level of these three lncRNAs." (PMID 34540695, 2021). "Similar to the function of these lncRNAs reported in other types of tumors, in our study, knockdown of DGCR10 and HAR1B promoted, whereas knockdown of SNHG18 inhibited the migration and invasion of glioma cells." (PMID 34540695, 2021). "To verify the effects of these lncRNAs on the migration and invasion of glioma cells, we knocked down the expressions of DGCR10, HAR1B, and SNHG18 in glioma cells, and the knockdown efficiency was verified in T98G cells." (PMID 34540695, 2021). "SNHG18 promoted the radioresistance of glioma cells and the metastasis of non-small cell lung cancer." (PMID 34211979, 2021). "In our previous study, we showed that lncRNA SNHG18 promoted glioma radioresistance by inhibiting semaphorin5A." (PMID 32934196, 2020). "In glioma, high SNHG18 expression enhances radiation resistance, and triggers EMT by increasing ENO1 expression." (PMID 33028341, 2020). "A recent study showed that inhibiting SNHG18 reduced the radioresistance of glioma cells via Sema5A." (PMID 31391206, 2019). "The ability of SNHG18 to regulate glioma cell motility depends on disrupting ENO1 nucleocytoplasmic transport." (PMID 31798634, 2019). "Taken together, the results of the present study revealed that increased expression of lncRNA SNHG18 promoted the invasive and migratory ability of glioma cells by regulating EMT progression and cytoskeleton remodeling." (PMID 31798634, 2019). "Though ENO1 did not affect the radiosensitivity significantly, knockdown of ENO1 expression using a small interfering RNA significantly suppressed the invasion-promoting action induced by SNHG18-overexpression in glioma cells." (PMID 31798634, 2019). "SNHG18 was reported to enhance cell motility and cytoskeletal remodeling in glioma cells." (PMID 38426128, 2024). "In this study, based on bioinformatics analysis, we hypothesized that SNHG18 could promote glioma progression via modulating microRNA-338-5p (miR-338-5p) and forkhead box D1 (FOXD1)." (PMID 34937497, 2022). "Subsequently, we divided the 47 glioma patients into high and low SNHG18 expression groups." (PMID 34937497, 2022). "Additionally, we investigated the regulatory effects of E2F transcription factor 1 (E2F1) on SNHG18, to explain the mechanism of SNHG18 dysregulation in glioma." (PMID 34937497, 2022). "Additionally, SNHG18 expression in glioma cell lines was significantly higher than in human astrocyte NHA." (PMID 34937497, 2022). "Subsequently, qRT-PCR data suggested that SNHG18 expression was up-regulated in glioma tissues." (PMID 34937497, 2022).
glioma (continued). "To determine whether SNHG18 participates in glioma progression by adsorbing miR-338-5p, we co-transfected si-SNHG18#1+ miR-338-5p inhibitors into U251 and T98G cells, and qRT-PCR validated the successful transfection." (PMID 34937497, 2022). "It was revealed that, SNHG18 expression in glioma was up-regulated and associated with unfavorable prognosis of the patients; knockdown of SNHG18 repressed the malignant biological behaviors of glioma cells, enhanced E-cadherin expression and repressed N-cadherin and Vimentin expressions." (PMID 34937497, 2022). "Moreover, the StarBase database indicated that E2F1 expression was in positive correlation with SNHG18 expression in glioma tissues." (PMID 34937497, 2022). "For example, SNHG18 knockdown suppressed metastasis and invasion of gliomas." (PMID 35359593, 2022). "Additionally, herein, we also provided an explanation of the mechanism of SNHG18 dysregulation in glioma." (PMID 34937497, 2022). "Next, we explored the mechanism of SNHG18 dysregulation in gliomas." (PMID 34937497, 2022). "Bioinformatics analysis tool LncBase Predicted V2.0 showed that miR-338-5p could probably be a target miRNA of SNHG18, and qRT-PCR showed that miR-338-5p expression was decreased in glioma cell lines." (PMID 34937497, 2022). "In conclusion, SNHG18 accelerates glioma progression via regulating the miR-338-5p/FOXD1 axis." (PMID 34937497, 2022). "Upregulation of SNHG18 promotes resistance to radiotherapy in glioma by repressing Semaphorin 5A." (PMID 34950662, 2021). "SNHG18 promotes glioma resistance to radiotherapy by repressing semaphorin 5A." (PMID 34288803, 2021). "In addition, SNHG18 promoted radiological resistance of glioma by inhibiting semaphore 5A and promoted glioma cell movement by disrupting α-enolase nucleoplasmic transport." (PMID 34408772, 2021). "Among the nine EMT-related lncRNAs identified in this study, LINC00900, MIR210HG, MIR22HG, PVT1, and SNHG18 were positively correlated with glioma malignancy, whereas HAR1A, LINC00641, SLC25A21-AS1, and SNAI3-AS1 were negatively correlated with glioma malignancy." (PMID 34288803, 2021). "The present study showed that SNHG18 promoted the invasive and migratory abilities of glioma cells." (PMID 31798634, 2019). "In the present study, we showed that SNHG18 promoted the invasion and migration of glioma cells." (PMID 31798634, 2019). "Our data proved that the SNHG18 may promote glioma progression by absorbing miR-338-5p." (PMID 34937497, 2022). "Importantly, the expressions of SNHG18 and miR-338-5p were negatively correlated in glioma cells." (PMID 34937497, 2022). "Additionally, knocking down SNHG18 repressed the malignant phenotypes of glioma cells." (PMID 34937497, 2022). "Thus, SNHG18 overexpression's effects on glioma cells depended at least in part on ENO1." (PMID 31798634, 2019). "SNHG18, NEAT1, LINC00339) and low expression of four lncRNAs (DICER1.AS1, NNT.AS1, WAC.AS1, TTC28.AS1 were with poor prognosis in glioma." (PMID 35237509, 2022). "Compared with non-tumor brain tissues, the expression levels of SNAI3-AS1, GDNF-AS1, WDFY3-AS2, and CPB2-AS1 showed an overall downward trend, and the expression level of SBF2-AS1, PAXIP1-AS2, SNHG18, and PVT1 showed an overall upward trend in glioma tissues." (PMID 34095147, 2021). "SNHG18 inhibits the nuclear and cytoplasmic transport of ENO1 to promote the occurrence and metastasis of glioma." (PMID 34215720, 2021). "However, besides radiosensitivity, the other functions of SNHG18 in glioma remain unclear." (PMID 31798634, 2019). "In summary, SNHG18 regulates the progression of EMT and the organization of the cytoskeleton into lamellipodia by repressing the nucleocytoplasmic transport of ENO1 in glioma cells." (PMID 31798634, 2019). "Indeed, previous studies in cancers have shown that SNHG18 promotes FOXD1 expression by decoying miR-338-5p,75 suppresses nucleocytoplasmic transport of α-enolase, and inhibits semaphorin 5A31 in glioma cells." (PMID 38498586, 2024).
glioma (continued). "We hypothesized that SNHG18 could facilitate the progression of glioma, and we demonstrated that SNHG18 could regulate the malignant biological behaviors of glioma cells and E2F1 bound to the SNHG18 promoter region to promote SNHG18 transcription." (PMID 34937497, 2022). "To determine whether SNHG18's glioma cell motility promotion ability involves ENO1, we utilized SNHG18 overexpressed glioma U251 cells with simultaneous suppression of ENO1 using a specific siRNA, siENO1." (PMID 31798634, 2019). "Our recent work revealed that the expression of lncRNA SNHG18 was related to the clinical tumor grade and showed a negative correlation with mutations of IDH1 in glioma." (PMID 31798634, 2019). "Thus, the interaction between SNHG18 and ENO1 probably regulates the nucleocytoplasmic transport of ENO1 in glioma cells." (PMID 31798634, 2019). "Furthermore, Pearson’s correlation analysis showed that SNHG18 expression was in negative correlation with miR-338-5p expression in glioma samples." (PMID 34937497, 2022). "Moreover, rather than altering ENO1 expression, SNHG18 suppressed its nucleocytoplasmic transport by directly combining with ENO1 in glioma cells." (PMID 31798634, 2019). "However, our previous study did not clarify the other functions of SNHG18 in glioma in addition to radiosensitivity." (PMID 31798634, 2019). "Currently, there is no data about SNHG18 expression pattern in glioma tissue." (PMID 30583549, 2018). "Pearson’s correlation analysis manifested that FOXD1 mRNA expression was in negative correlation with miR-338-5p mimics in glioma samples; FOXD1 mRNA was positively correlated with SNHG18 expression." (PMID 34937497, 2022). "For example, the binding sites of SNHG18 and ENO1 were not identified, and the upstream mechanism regulating SNHG18 expression in glioma is unclear." (PMID 31798634, 2019).
multiple myeloma (4 papers, 2021 to 2023). "Reportedly, SNHG18 is highly expressed in multiple myeloma (MM), which is closely related to Mayo Clinic Risk Stratification for MM and the short overall survival time." (PMID 34937497, 2022). "In patients with newly diagnosed multiple myeloma, SNHG18 and its possible target gene SEMA5A are upregulated, and high expression are related to poor prognosis." (PMID 36927398, 2023). "High expression of SNHG18 may be a marker of poor prognosis in multiple myeloma (MM)." (PMID 34540695, 2021).
non-small cell lung carcinoma (4 papers, 2021 to 2024). A group of at least three distinct histological types of lung cancer, including non-small cell squamous cell carcinoma, adenocarcinoma, and large cell carcinoma. "The high SNHG18 expression in non-small cell lung cancer is related to lymph node metastasis and a decreased overall survival rate." (PMID 36927398, 2023). "Mechanically, SNHG18 acts as a lncRNA mediator of MKL1 in non-small cell lung cancer, facilitating NSCLC growth and metastasis by modulating the miR-211-5p/BRD4 axis." (PMID 36927398, 2023). "Furthermore, mkl1-induced SNHG18 regulates the metastasis and growth of non-small cell lung cancer by modulating the miR-211-5p/BRD4 pathway." (PMID 35359593, 2022).
hepatocellular carcinoma (3 papers, 2020 to 2023). A malignant tumor that arises from hepatocytes. "SNHG18 was identified to play as a tumor suppressor gene in hepatocellular carcinoma." (PMID 33363029, 2020).
bladder cancer (2 papers, 2023). "Mechanism studies have shown that SNHG18 promotes the transcription and expression of p21 by inhibiting c-Myc expression, leading to G0-G1 arrest and inhibiting the proliferation of bladder cancer cells." (PMID 36927398, 2023). "In vivo and in vitro functional experiments revealed the biological function of SNHG18 to significantly inhibit the proliferation of bladder cancer cells." (PMID 36927398, 2023). "Upregulation of SNHG18 reduced proliferation of bladder cancer cells and decreased tumor sizes in mice." (PMID 37215134, 2023). "The specific mechanism of SNHG18 inhibition of bladder cancer proliferation was studied by flow cytometry, western blotting, dual luciferase reporter gene assay and protein degradation assay." (PMID 36927398, 2023). "The expression of SNHG18 was evaluated by RT-qPCR in bladder cancer clinical samples and human bladder cancer cell lines, and stable cell lines overexpressing SNHG18 were constructed." (PMID 36927398, 2023). "SNHG18 impaired the expression of c-Myc via targeting its ubiquitination and degradation, resulting in p21 upregulation in bladder cancer." (PMID 37215134, 2023). "SNHG18 promotes the transcription and expression of p21 by inhibiting c-Myc expression, leading to G0-G1 arrest and inhibiting the proliferation of bladder cancer cells." (PMID 36927398, 2023). "The bladder cancer patients with high expression of SNHG18 had a better survival rate." (PMID 37215134, 2023).
liver cancer (2 papers, 2022 to 2023). An epithelial or non-epithelial malignant neoplasm that arises from the liver. "SNHG18 is downregulated and can be used as an independent diagnostic index in liver cancer." (PMID 36927398, 2023). "Conversely, in liver cancer, SNHG18 is considered to be a tumor suppressor." (PMID 34937497, 2022).
lymph node metastasis (2 papers, 2021 to 2023). "Multivariate Cox regression analysis demonstrated that SNHG18 expression (P = 0.004) and lymph node metastasis (P = 0.029) were independent risk factors for NSCLC patients." (PMID 33500406, 2021). "SNHG18 upregulation in NSCLC specimens correlated with lymph node metastasis and reduced overall survival of NSCLC patients." (PMID 33500406, 2021). "Moreover, high SNHG18 expression was significantly correlated with lymph node metastasis (P = 0.0017)." (PMID 33500406, 2021).
Cirrhosis (1 paper, 2026). A chronic disorder of the liver in which liver tissue becomes scarred and is partially replaced by regenerative nodules and fibrotic tissue resulting in loss of liver function. "Among HCC patients exhibiting AFP levels below 200 ng/mL, SNHG18 shows comparatively high sensitivity and specificity relative to cirrhosis patients and healthy controls, with sensitivity at 75.61% and specificity at 73.49%." (PMID 41474641, 2026). "Specifically, plasma levels of SNHG18 are significantly reduced in HCC patients when compared to healthy controls, patients with hepatitis B, or those with cirrhosis." (PMID 41474641, 2026).
glioblastoma (1 paper, 2021). The most malignant astrocytic tumor (WHO grade IV). "High expressions of PVT1 and SNHG18 in glioblastoma samples as opposed to LGG was validated in the previous study." (PMID 34950662, 2021).